SNX22 (sorting nexin 22)
Description:
May be involved in several stages of intracellular trafficking (By similarity). Interacts with membranes containing phosphatidylinositol 3-phosphate (PtdIns(3P)).
Synonyms: FLJ13952
Tractability: Antibody: UniProt places it where antibodies can reach, with medium confidence.
Gene: Protein-coding gene on chromosome 15 (64,151,713 to 64,157,481, forward strand). Ensembl gene ENSG00000157734.
Subcellular location: Cytoplasmic vesicle membrane
Subcellular location (Human Protein Atlas): Vesicles; Nucleoplasm
Gene Ontology:
Molecular function: protein binding; phosphatidylinositol phosphate binding; phosphatidylinositol binding
Cellular component: cytoplasmic vesicle membrane
Genetic constraint (gnomAD): Loss-of-function variants: 23 observed, 20.87 expected, observed/expected ratio (o/e) 1.1, 90% interval 0.79 to 1.56. The upper end of that interval is the gene's LOEUF score, 1.56, which puts it in group 6 of 6, group 1 being the genes least tolerant of losing a copy. Missense variants: 261 observed, 229.68 expected, observed/expected ratio (o/e) 1.14, 90% interval 1.03 to 1.26. Synonymous variants: 99 observed, 95.62 expected, observed/expected ratio (o/e) 1.04, 90% interval 0.88 to 1.22.
Homologues: Orthologues: chimpanzee SNX22 (99% identical), macaque SNX22 (96% identical), mouse Snx22 (83% identical), guinea pig SNX22 (82% identical), dog SNX22 (80% identical), pig SNX22 (80% identical), rabbit SNX22 (73% identical), rat Snx22 (66% identical), tropical clawed frog snx22 (50% identical), zebrafish snx22 (41% identical). Paralogues in human: SNX24 (43% identical).
Diseases named in the same sentence as SNX22 in open-access papers:
SNX22 is named in the same sentence as 6 diseases in open-access papers, as found by Europe PMC text mining. Sharing a sentence is not in itself a finding about the gene and the disease. The quoted sentences say what the papers report.
breast carcinoma (1 paper, 2025). "Together, ZNF32 H179A and H183A promote the proliferation of breast cancer cells by differentially upregulating ISY1-RAB43 and UPK3BL1 as well as downregulating SNX22 expressions." (PMID 40046230, 2025).
congenital cataracts (1 paper, 2023). "One study report that Snx22 may play a role in the development of congenital cataracts, due to altered expression in cataractous lenses compared to controls." (PMID 37118843, 2023).
cancer (1 paper, 2024). A tumor composed of atypical neoplastic, often pleomorphic cells that invade other tissues. "On the other hand, some genes’ function such as SNX22 and SLC2A13 were scarcely reported in cancer." (PMID 39538125, 2024).
SNX22 also shares sentences with these, for which no sentence is quoted: astrocytoma (1 paper); autoimmune disease (1); tumor (1).